NFIX (nuclear factor I X)
Diseases named in the same sentence as NFIX in open-access papers (continued):
Sharing a sentence is not in itself a finding about the gene and the disease.
gastric cancer (11 papers, 2008 to 2025). A primary or metastatic malignant neoplasm involving the stomach. "In addition, reduced NFIX expression was significantly associated with worse FP in gastric cancer patients." (PMID 32219034, 2020). "The nuclear factor I X (NFIX) was discovered to regulate chromatin access and maintain CSC identity, and high levels of NFIX expression in gastric cancer were associated with increased tumor stemness and poorer patient prognosis." (PMID 40277903, 2025). "In a recent study, LINC00511 was also found to foster the process of gastric cancer by targeting miR-625-5p/NFIX axis." (PMID 32698787, 2020). "In the context of gastric cancer, NFIX influences cellular growth by modulating stemness." (PMID 40000619, 2025). "LINC00511 is a tumor promoter that sponges miR-625-5p by targeting NFIX in gastric cancer cells and could be considered a brand new target for gastric cancer treatment." (PMID 34337069, 2021). "Low expression of NFIC and NFIX predicted poor OS in gastric cancer patients." (PMID 32219034, 2020). "Existing research verified that NFIX acted as an oncogene in gastric cancer." (PMID 33298078, 2020). "miR-1915-3p modulated the development of gastric cancer and colorectal cancer through the repression of RAGE, NFIX, and BCL-2." (PMID 39123189, 2024). "In gastric cancer, LINC00511 promotes tumorigenesis through the regulation of the miR-625-5p/NFIX circuit." (PMID 35893227, 2022). "In gastric cancer, high NFIX expression was significantly correlated with better overall prognosis in gastric cancer and HER2+ gastric cancer, and marginally correlated with PPS in HER2-gastric cancer." (PMID 32219034, 2020). "It is thus of some interest that the chromosomal region 19p13.3, the location of NFIX, appears frequently deleted in some, however not all series of gastric cancers." (PMID 18482459, 2008). "Finally, miR-625-5p/NFIX, miR-124-3p/EZH2, miR-625-5p/STAT3 and miR-29b/KDM2A are other molecular axes regulated by LINC00511 in gastric cancer." (PMID 37124625, 2023). "For gastric cancer, NFIB and NFIX mRNA levels were not significantly different between tumor and normal tissues." (PMID 32219034, 2020).
glioma (11 papers, 2009 to 2025). A benign or malignant brain and spinal cord tumor that arises from glial cells (astrocytes, oligodendrocytes, ependymal cells). "NFIX gene expression has been shown to be significantly lower in some tumors (medulloblastoma, colorectal cancer or glioma), where it has been implicated as a tumor suppressor gene." (PMID 34299133, 2021). "Like NFIB, NFIA and NFIX also have been implicated in glioma." (PMID 27083054, 2016). "Our attempts to establish stable NFIX over-expression systems in human glioma cell lines were unsuccessful and in U-251 MG cells, we did observe loss of cell division in cells transfected with NFIX expressing plasmid (Singh and Westermark, unpublished results)." (PMID 19337383, 2009). "Circ-NFIX was the only circRNA overexpressed in glioma using five different experimental approaches." (PMID 35883576, 2022). "The exosomal circRNA NFIX mediates the resistance of gliomas to temozolomide at least in part by sponging miR-13290." (PMID 35352001, 2022). "The lowest concentration of the target biomolecules, detectable in our experiments, was of the order of ~10−17 M. The SOI-NR sensor chips proposed herein have allowed us to reveal an elevated level of the NFIX circular RNA in the blood of a glioma patient." (PMID 34356707, 2021). "Here we show that nuclear factor IX (NFIX) is significantly upregulated in human GBM lesions compared with normal or low-grade gliomas." (PMID 32291386, 2020). "IHC staining showed that the NFIX was increased in low-grade glioma samples, and even further enriched in the GBM." (PMID 32291386, 2020). "Retroviral tagging using MMULV expressing PDGFB to identify novel glioma-causing genes gave one integration in NFIA, NFIB and NFIC each and five integrations in NFIX." (PMID 19337383, 2009). "circRNA NFIX has been shown to exist as an oncogene in glioma." (PMID 39135128, 2024). "Previous research hinted that temozolomide resistance in glioma was enhanced by circRNA NFIX." (PMID 39135128, 2024). "Additionally, circ-NFIX was shown in vivo to inhibit glioma growth via the regulation of miR-34a-5p and NOTCH1." (PMID 35883576, 2022). "Moreover, in glioma, one study revealed that the expression of exosomal circRNA NFIX was significantly increased in the serum of patients with temozolomide resistance." (PMID 35352001, 2022). "Circ-NFIX expression was significantly increased in glioma cells." (PMID 35883576, 2022). "Regarding NFIX, 22 datasets revealed lower NFIX expression levels in 10 types of carcinomas with statistical significance, however, 10 analyses showed higher NFIX expression levels in brain and CNS cancer, esophageal cancer, melanoma, prostate cancer and sarcoma." (PMID 32219034, 2020). "Additionally, a miR-34a-5p inhibitor abolished si-suppressive circ-NFIX’s impact on glioma cells." (PMID 35883576, 2022). "Circ-NFIX may enhance glioma growth via the Notch signaling pathway by sponging miR-34a-5p." (PMID 35883576, 2022). "Additionally, the “ErbB Signaling Pathway,” “Tight Junction,” “Glioma,” and “Small Cell Lung Cancer” pathways are also prominently represented, further highlighting the broad regulatory impact of NFIA, NFIB, NFIC, and NFIX on several types of cancer." (PMID 39617063, 2025). "Interestingly then, HSF1 expression in glioma cell line U-343 MG-Cl2:6 with low NFIX expression was not sensitive to NFIX-siRNA." (PMID 19337383, 2009). "Since tyrosine phosphorylation is one of the first steps in growth factor receptor signaling activated in tumorigenesis, our findings raise possibilities that NFIX could be a substrate for some oncogenic growth factor such as PDGFB, with which it has been shown to cooperate in glioma formation." (PMID 19337383, 2009).
colorectal cancer (9 papers, 2019 to 2024). A primary or metastatic malignant neoplasm that affects the colon or rectum. "Only NFIX expression was associated with OS in colorectal cancer patients." (PMID 32219034, 2020). "In colorectal cancer, high NFIX expression levels were associated with chemotherapy resistance." (PMID 31766658, 2019). "These miRNAs were shown to promote the proliferation and migration of colorectal cancer cells, functioning as oncogenes, possibly by directly targeting and downregulating NFIX." (PMID 36901722, 2023). "In cases of endometrial carcinoma and colorectal cancer, NFIX downregulation has been shown to promote proliferation, in line with our findings in NSCLC." (PMID 37686043, 2023). "Opposite to the tumor-promoting role in the GBM, NFIX inhibits the migration of cancer cells in both esophageal squamous cell carcinoma and colorectal cancer." (PMID 32291386, 2020). "By contrast, another study found that miR-1914 helped suppress the chemoresistant abilities of colorectal cancer cells also by nuclear factor I/X (NFIX) downregulation." (PMID 31766385, 2019). "For example, NFIX downregulation has been shown to reduce proliferation and cell viability in lung cancer but to lead to increased proliferation in the context of endometrial carcinoma and colorectal cancer." (PMID 36901722, 2023). "Down-regulation of miR-1915-3p was responsible for multidrug resistance in colorectal cancer, and re-establishing miR-1915-3p could restore the chemosensitivity depend on suppression of BCL-2 and NFIX expression." (PMID 34774019, 2021).
Intellectual disability (9 papers, 2014 to 2026). "It is the first time to report variants in EFNB1, NAA10, DHCR7, LAMA1 and NFIX in Chinese intellectual disability/developmental delay patients and first report about variants in NAA10 and LAMA1 in affected individuals of Asian ancestry." (PMID 31088393, 2019). "In conclusion, we suggest that deletions involving NFIX gene should be considered in patients with overgrowth during childhood, macrocephaly, developmental delay, and seizures, as well as severe intellectual disability." (PMID 31574590, 2019). "Deletions involving NFIX gene should be considered in patients with overgrowth during childhood, macrocephaly, developmental delay, and seizures, as well as severe intellectual disability." (PMID 31574590, 2019). "Interestingly, 19p13 microduplications encompassing NFIX are responsible for intellectual disability, short stature, and small head circumference." (PMID 33842847, 2021).
lung cancer (9 papers, 2017 to 2025). A malignant neoplasm involving the lung. "Low expression of NFIX has been reported in lung cancer, where it is associated with a poor prognosis." (PMID 40000619, 2025). "In comparison to normal lung cells, there was a substantial rise in circRNA NFIX expression in lung cancer cell lines, accompanied by a decrease in miR‐214‐3p levels." (PMID 39135128, 2024). "NFIX was recently described as a master regulator activating the expression of 17 genes that are involved in migration and invasion in lung cancer." (PMID 36901722, 2023). "Silencing of NFIX expression can inhibit the proliferation, migration, and invasion of lung cancer cell lines." (PMID 33988228, 2021). "In lung cancer, silencing of NFIX induced a decrease in IL6ST, TIMP1, and ITGB1 gene expression and reduced cell proliferation, migration, and invasion processes." (PMID 31766658, 2019). "Using two different cell lines for lung cancer, it was shown that NFIX regulates interleukin-6 receptor subunit β (IL6ST), metalloproteinase inhibitor 1 (TIMP1), and integrin β-1 (ITGB1) genes, all of which are involved in cell proliferation, migration, and invasion." (PMID 36901722, 2023). "Another RAC GTPase and catalytic subunit of NADPH oxidase, RAC2, has also been described to promote transcriptional activation of JUNB in lung cancer (Figure 3iii), which could be yet another mechanism that leads to NFIX activation." (PMID 36901722, 2023). "We suggest that NFIX is a master regulator that regulates metastasis in lung cancer by transcribing the genes responsible in activating the pathways leading to micrometastasis and finally cause the cancer cells to metastasize such as inflammation, proliferation, migration and invasion." (PMID 28871224, 2017). "Additionally, NFIX serves as a key regulator in lung cancer." (PMID 40000619, 2025). "Hence, NFIX with IL6ST, TIMP1, ITGB1, PTCH1, GGCX and NFAT5 genes may regulate the migration and invasion process and they could serve as potential therapeutic targets in patients with lung cancer to predict survival and improve prognosis." (PMID 28871224, 2017).
Marshall-Smith syndrome (8 papers, 2013 to 2026). "Pathogenic variants in the NFIX gene have also been reported in individuals with Marshall-Smith syndrome." (PMID 42311878, 2026). "Specifically, frameshift and splice mutations in NFIX resulted in Marshall-Smith syndrome (MSS) while NFIX deletions and nonsense mutations cause a Sotos-like overgrowth syndrome." (PMID 27688808, 2016). "Mutations in NFIX had been linked to a known clinical condition, Marshall-Smith syndrome (MSS, OMIM#602535)." (PMID 27688808, 2016). "Recently, it was shown that haploinsufficiency for NFIX is one of the causative factors for both Sotos syndrome and Marshall-Smith syndromes." (PMID 23776487, 2013). "For example, accurate detection could translate into completely different genetic syndromes, e.g., Marshall-Smith syndrome or overgrowth syndrome for different exons of the NFIX gene." (PMID 33584815, 2020). "In a cohort of patients with a clinical diagnosis of autosomal dominant Marshall-Smith syndrome (MRSHSS; OMIM: #602535), a recurrent deletion of the NFIX gene was identified using multiplex ligation-dependent probe amplification (MLPA) after negative NFIX sequencing." (PMID 36672937, 2023).
Sotos syndrome (7 papers, 2013 to 2023). Sotos syndrome is a rare multisystemic genetic disorder characterized by a typical facial appearance, overgrowth of the body in early life with macrocephaly, and mild to severe intellectual disability. "We also identified a case of 19p13.2 duplication involving the NFIX gene associated with a Sotos syndrome-like phenotype." (PMID 29441128, 2018). "Taken together, these data highlight the importance of NFIX for the normal formation and function of the hippocampus and may provide insights into the underlying basis of the neurological symptoms associated with disorders such as Sotos syndrome, in which mutations in NFIX have been implicated." (PMID 23776487, 2013).
glioblastoma (5 papers, 2009 to 2025). The most malignant astrocytic tumor (WHO grade IV). "Though the Nuclear factor 1 family member NFIX has been strongly implicated in PDGFB-induced glioblastoma, its molecular mechanisms of action remain unknown." (PMID 19337383, 2009). "Considering the important role of the NFI family in neuronal development, several studies have analyzed NFIX’s role in glioblastomas as a potential tumor-promoter." (PMID 36901722, 2023). "One such study found that NFIX promotes glioblastoma cell migration by directly upregulating the expression of EZR (encoding ezrin), which is involved in linking the actin cytoskeleton and the plasma membrane and plays a role in cell migration." (PMID 36901722, 2023). "NFIX regulates the proliferation and DNA damage response of glioblastoma multiforme (GBM) cells through transcriptional activation of GINS1." (PMID 40000619, 2025).
pancreatic cancer (5 papers, 2020 to 2025). "For example, MAFG-DT enhanced pancreatic cancer cell proliferation and invasion, whereas it inhibited apoptosis by sponging miR-3196 to upregulate the expression of NFIX." (PMID 39735608, 2024). "MAFG-AS1, for example, increases pancreatic cancer development by increasing NFIX." (PMID 37686043, 2023). "However, overexpression of NFIX can promote proliferation and apoptosis in pancreatic cancer cells." (PMID 37686043, 2023). "The lncRNA MAFG-AS1 has been shown to promote cell proliferation and migration in drug-resistant hepatocellular carcinoma (HCC) and pancreatic cancer by sponging miR-3196, leading to the upregulation of STRN4 and NFIX, respectively." (PMID 40004152, 2025).
developmental delay (4 papers, 2019 to 2026). "The WES approach allowed us to identify five clinically relevant variants in the GZF1, NFIX, TRRAP, FGFR2 and PAX2 genes associated with Larsen, Malan, developmental delay with or without dysmorphic facies and autism, LADD1 and papillorenal syndromes." (PMID 38909058, 2024).
esophageal squamous cell carcinoma (4 papers, 2019 to 2025). Esophageal squamous cell carcinoma (ESCC) is a type of esophageal carcinoma (EC) that can affect any part of the esophagus, but is usually located in the upper or middle third. "In contrast, in esophageal squamous cell carcinoma, low NFIX expression was associated with positive lymph node metastasis and advanced tumor-node-metastasis stage." (PMID 31766658, 2019). "In esophageal squamous cell carcinoma, NFIX has been shown to reduce cell proliferation and induce G1/G0 cell cycle arrest." (PMID 40000619, 2025). "On the other hand, overexpression of NFIX in esophageal squamous cell carcinoma has been shown to reduce cell proliferation and induce cell cycle arrest in G1/G0 phase." (PMID 36901722, 2023). "NFIX has been shown to be involved in the progression of esophageal squamous cell carcinoma and colorectal cancer." (PMID 32291386, 2020). "NFIX has been shown to play a role in regulation of muscle development, hematopoiesis, and also be involved in the development of prostate cancer, esophageal squamous cell carcinoma and colorectal cancer." (PMID 32291386, 2020). "An inverse correlation between the levels of miR-1290 and NFIX protein and mRNA was observed in esophageal squamous cell carcinoma tissue samples, suggesting that miR-1290 is an oncogene that downregulates NFIX and promotes proliferation, migration, and invasion in this type of tumor." (PMID 36901722, 2023).
ovarian carcinoma (4 papers, 2018 to 2021). A malignant neoplasm originating from the surface ovarian epithelium. "Moreover, miR-744-5p was reported to facilitate cell apoptosis by targeting HNRNPC and NFIX in ovarian cancer.In this study, CDCA4 was identified as the target gene of miR-744-5p and was negatively regulated by miR-744-5p." (PMID 34090440, 2021).
autism (3 papers, 2024 to 2025). Persistent deficits in social interaction and communication and interaction as well as a markedly restricted repertoire of activity and interest as well as repetitive patterns of behavior. "NFIX has been predicted to target 28 autism risk genes, including DIP2C and CSNK1E." (PMID 39363111, 2024).
epilepsy (3 papers, 2018 to 2023). A brain disorder characterized by episodes of abnormally increased neuronal discharge resulting in transient episodes of sensory or motor neurological dysfunction, or psychic dysfunction. "Individuals with NFIX microdeletions present with a significantly higher frequency of epilepsy and EEG anomalies than those carrying NFIX intragenic variants, possibly because of the involvement of adjacent genes contributing to the clinical phenotype in the frame of a contiguous gene disorder." (PMID 39816865, 2023). "No significant clinical differences have been observed among individuals with intragenic NFIX variants or NFIX gene deletions, except for a significantly higher frequency of epilepsy and EEG anomalies in MS individuals carrying NFIX microdeletions." (PMID 35887841, 2022).
Hydrocephalus (3 papers, 2018 to 2024). Hydrocephalus is an active distension of the ventricular system of the brain resulting from inadequate passage of CSF from its point of production within the cerebral ventricles to its point of absorption into the systemic circulation. "To investigate the role of NFIX in hydrocephalus, we examined ependymal cells in brains from postnatal Nfix−/− and control (Nfix+/+) mice using a combination of confocal and electron microscopy." (PMID 35954220, 2022). "In Nfix−/− mice, hydrocephalus becomes fully penetrant in the early postnatal period, but the contribution of NFIX to ependymal cell development remains unclear." (PMID 29452604, 2018).
lung adenocarcinoma (3 papers, 2020 to 2023). A carcinoma that arises from the lung and is characterized by the presence of malignant glandular epithelial cells. "In addition, the NFIX expression in lung adenocarcinoma (LUAD) was associated with the clinicopathological stage." (PMID 37686043, 2023). "The results showed that NFIX was downregulated in tumor tissues compared to normal tissues in lung adenocarcinoma (LUAD) and lung squamous carcinoma (LUSC)." (PMID 37686043, 2023).
Macrocephaly (3 papers, 2021 to 2025). Occipitofrontal (head) circumference greater than 97th centile compared to appropriate, age matched, sex-matched normal standards. "Brain growth disorders as micro- (ASPM, MCPH1) and macrocephaly (NFIX, GLI3) have been highlighted as relevant for the evolution in humans due to the impact in early brain development." (PMID 36550402, 2022).
breast invasive carcinoma (2 papers, 2020 to 2023). "NFIX mRNA level was significantly reduced in multiple databases including Curtis, Zhao, Kamoub and Gluck for invasive ductal breast carcinoma, invasive ductal and invasive lobular breast carcinoma, invasive ductal breast carcinoma and invasive breast carcinoma, respectively." (PMID 32219034, 2020). "Breast invasive carcinoma patients with a NFIX gene alteration showed significantly poor overall survival (OS) and disease-free survival (DFS) compared with breast invasive carcinoma patients without NFIX gene alteration." (PMID 32219034, 2020).
cervical squamous cell carcinoma (2 papers, 2020 to 2023). A squamous cell carcinoma arising from the cervical epithelium. "The results showed lower mRNA expression of NFIB, NFIC and NFIX predicted worse OS in cervical squamous cell carcinoma." (PMID 32219034, 2020).